HMGB3P1 (high mobility group box 3 pseudogene 1)
Synonyms: dJ18C9.3; formerly HMG4L; HMGB3L1
Gene: Processed pseudogene on chromosome 20 (34,833,575 to 34,834,462, reverse strand). Ensembl gene ENSG00000225336.
Diseases named in the same sentence as HMGB3P1 in open-access papers:
HMGB3P1 is named in the same sentence as 1 disease in open-access papers, as found by Europe PMC text mining. Sharing a sentence is not in itself a finding about the gene and the disease. The quoted sentences say what the papers report.
tumor (2 papers, 2020 to 2025). "Moreover, Xue and colleagues reported that HMGB3P1 is upregulated in CRC tissues compared to the corresponding non‐tumor tissues." (PMID 40556338, 2025). "To further screen out the desired lncRNAs, we utilized RT-qPCR assay to identify the top 5 lncRNAs (PCAT7, FAM83C-AS1, LINC00144, HMGB3P1 and AC016735.1) that were remarkably upregulated in CRC tissues as compared to corresponding non-tumor tissues." (PMID 33109776, 2020).